IL2 (interleukin 2)
Diseases named in the same sentence as IL2 in open-access papers (continued):
Sharing a sentence is not in itself a finding about the gene and the disease.
autoimmune disease (continued). "Deficiency of IL-15 leads to a profound depletion of NK cells, NKT cells, intestinal intraepithelial lymphocytes and CD8+ memory T cells, whereas deficiency of IL-2 leads to lymphoproliferative and autoimmune disease." (PMID 21408124, 2011). "IL-2 is a well-known T cell growth factor, yet, IL-2 deficiency is associated with severe multi-organ autoimmune disease characterised by the overproduction of IL-17." (PMID 19333372, 2009). "These include a region on chromosome 4q27 that contains genes for interleukin 2 and interleukin 21 that has been recently implicated in other autoimmune diseases, and seven additional regions that include chromosome 13q13 and 15q21." (PMID 18369459, 2008). "Our results suggest that distant variants upstream of IL21 could also be important for human autoimmune diseases that have been found to be associated with the IL21/IL2 chromosome region." (PMID 39746095, 2025). "It will be interesting to learn whether human cases of autoimmune diseases that map to the IL21/IL2 locus carry specific variants in the region syntenic to the 39 kb deletion." (PMID 39746095, 2025). "IL-2 is an essential cytokine for the development and function of Tregs, and mice with a deletion of the gene encoding its receptor, IL-2RB, fail to produce a normal subset of Tregs, suggesting that autoimmune diseases are associated with IL-2/IL-2 receptor gene deletion." (PMID 40746545, 2025). "Furthermore, Mice with deficiencies in IL-2 or the IL-2 receptor exhibit diminished Treg generation, precipitating autoimmune disorders." (PMID 38524638, 2024). "This concept is supported by observations showing that polymorphisms altering IL-2 signaling in humans are associated with autoimmune diseases, including type 1 diabetes, celiac disease, multiple sclerosis (MS), Graves’ disease, Sjögren’s syndrome, and rheumatoid arthritis." (PMID 38432631, 2024). "The IL2 gene encodes a cytokine with crucial, pleotropic roles in the immune system, and dysregulation of IL-2 and IL-2 receptor signaling leads to immunodeficiency and autoimmune disorders in mice and humans." (PMID 39302339, 2024). "A body of evidence has shown that Tregs are intrinsically defective in many common autoimmune diseases, and gene polymorphisms which increase the susceptibility of autoimmune disease development have implicated the interleukin-2 (IL-2) signaling pathway as a key dysregulated mechanism." (PMID 36399073, 2023). "Moreover, the relative deficiency of IL2 observed in the course of some autoimmune disorders contributes to the disturbance of Treg homeostasis, which reinforces the vicious circle of tolerance violation and the development of chronic inflammation." (PMID 37047033, 2023). "In addition, in some autoimmune diseases, a relative deficiency of IL-2 develops during disease pathogenesis leading to a disturbance of Treg homeostasis, which further amplifies the vicious cycle of tolerance breach and chronic inflammation." (PMID 33868284, 2021). "Previous studies have shown that people deficient in IL-2 can develop severe autoimmune diseases, possibly due to the uncontrolled proliferation of autoreactive T cells and B cells and the proliferation of immature, non-functional Tregs caused by these defects." (PMID 33882880, 2021). "Non-coding susceptibility alleles within UBASH3A are associated with several autoimmune diseases, including type 1 diabetes and RA, and are also associated with increased transcription, thereby leading to reduced transcription of interleukin-2 (IL2) in effector T cells." (PMID 32117312, 2020). "IL-2 activates Treg cells and is used to treat autoimmune diseases caused by Treg cell defects." (PMID 32063984, 2020). "Polymorphisms in IL-2, IL-2Rα, and IL-2Rβ are genetic risk factors for several autoimmune diseases." (PMID 31824482, 2019).
autoimmune disease (continued). "Indeed, the NOD Idd3 locus has been associated with reduced IL-2 expression, alterations in Treg cell pools and development of autoimmune diseases such as autoimmune diabetes, autoimmune ovarian dysgenesis, and autoimmune sialadenitis." (PMID 31824482, 2019). "We hypothesize that low-dose IL-2 may be a prime candidate therapy for other autoimmune diseases such as Rheumatoid Arthritis (RA) in which a deficiency in Treg cell number or function is present." (PMID 29527328, 2018). "The TAGAP gene encodes a member of the Rho GTPase-activator protein superfamily involved in T cell activation and co-regulation with IL-2, which has been previously associated with several autoimmune diseases, including rheumatoid arthritis, celiac disease, and multiple sclerosis." (PMID 27015091, 2016). "In addition, low levels of circulating IL-2 have been associated with different autoimmune diseases." (PMID 27242702, 2016). "We also report the significance of IL-2 in eliminating either the Tfh cells, which promote autoantibody production, or the pathogenic Th17 cells, both of which play a major role in the development of autoimmune diseases." (PMID 25322151, 2014). "We found that CD247, IL2RB and IL2 ranked 32th, 34th and 39th, respectively, and have been associated with RA in follow-up study of GWAS and studies exploring shared susceptibility loci among autoimmune diseases." (PMID 21980439, 2011). "Although IL-2 is well studied for association with autoimmune diseases, only a single study has investigated genetic association with risk for prostate cancer, implicating an indirect prostate cancer susceptibility marker, with no direct functional significance." (PMID 20184734, 2010). "Our findings show that Low-dose IL-2 therapy might particularly benefit autoimmune disease patients with increased risk of infection due to compromised immunity, such as reduced CD8+ T cell function, but caution should be taken to avoid potential CD8+ T cell-mediated immunopathology." (PMID 34618873, 2021). "These proofs showed the potential utility of IL-2/IL-2Rβ system for selective expansion of engineered T cells in autoimmune disorders." (PMID 40337274, 2025). "IL-2 is also crucial for the formation of Tregs and is essential for the function of Foxp3+ T cells in autoimmune diseases such as type 1 diabetes, systemic lupus erythematosus, pancreatitis, and pancreatic cancer." (PMID 39958351, 2025). "99mTc-IL2 was successfully used in patients with different inflammatory and autoimmune disorders and in melanoma." (PMID 40869484, 2025). "Correspondingly, CEACAM1 is highly induced on Tregs from patients with autoimmune disease undergoing low-dose IL-2 therapy, and these Tregs showed reduced proliferation." (PMID 40773294, 2025). "IL-2 mutants or IL-2 complexes designed to preferentially stimulate Treg are being tested in autoimmune diseases, graft-versus-host disease (GVHD), and transplantation tolerance." (PMID 41254515, 2025). "IL-2, secreted by Th1 cells, promotes T cell proliferation and immune tolerance, helping to prevent autoimmune diseases." (PMID 39833691, 2025). "In the past three decades, radiolabelled IL2 has demonstrated its potential for imaging activated T-lymphocytes in many autoimmune diseases and in different cancers." (PMID 40590904, 2025). "By combining IL-2/IL-2R system with engineered T cell-based immunotherapies to enhance the therapeutic efficacy of engineered T cells shows its potential in autoimmune diseases." (PMID 40337274, 2025). "Our genome-wide pleiotropy study further identified a gene cluster on the 4q27 chromosome region, encompassing KIAA1109, IL2, IL21, and ADAD1 genes, reporting a strong literature support for association with most autoimmune diseases and AD." (PMID 41009683, 2025). "Regarding IL-2, a recent clinical trial demonstrated clinical improvement in 13 autoimmune diseases with low doses of IL-2, which can specifically activate regulatory T cells." (PMID 41533941, 2025).
autoimmune disease (continued). "IL-2 has been exploited to selectively expand Treg cells in autoimmune diseases, while in cancer, expanding TEFF cells is desirable." (PMID 40680114, 2025). "Treg dysfunction is a well-established feature across autoimmune diseases and therapeutic strategies such as low-dose IL-2 have been shown promising in selectively expanding functional Tregs and restoring immune tolerance in early-phase clinical trials." (PMID 41332545, 2025). "This study uses a rat model of rheumatic heart disease to evaluate the potential of low-dose interleukin 2 therapy in improving clinical outcomes and reducing the incidence of autoimmune diseases triggered by streptococcal infections." (PMID 39998162, 2025). "O.B. and M.E.R. hold patents on improved IL-2 formulations and are shareholders of Seito Biologics AG, which develops improved IL-2 immunotherapies for autoimmune diseases." (PMID 40502703, 2025). "The functional relevance of this loop is explored in a chronic xenogeneic GVHD (xGVHD) model and in patients with autoimmune disease undergoing low-dose IL-2 therapy." (PMID 40773294, 2025). "Since IL-2 and TGF-β production and/or signaling can be deficient in autoimmune diseases including SLE, rheumatoid arthritis, type 1 diabetes, multiple sclerosis and inflammatory bowel disease, these abnormalities can contribute to Treg instability." (PMID 40799646, 2025). "IL2 is considered a tolerogenic cytokine as it prevents autoimmune diseases by promoting the differentiation of certain immature T-cells into regulatory T-cells and also promotes beta-cell proliferation." (PMID 38543910, 2024). "More recently, studies investigating low-dose IL-2 in autoimmune diseases have also shown encouraging results." (PMID 38426492, 2024). "Recent clinical studies have shown that low-dose IL-2 is safe and effective against 11 autoimmune diseases, including rheumatoid arthritis (RA) and ankylosing spondylitis." (PMID 38807592, 2024). "Trials of low dose interleukin-2 are currently underway to study the efficacy of low-dose IL-2 stimulation of Tregs in autoimmune disease." (PMID 38873035, 2024). "The IL-2/antibody fusion we discovered can potentially be used in the treatment of a broad spectrum of autoimmune diseases in human." (PMID 38461332, 2024). "A single-agent fusion of human IL-2 and antiIL-2 antibody is discovered and engineered to selectively expand regulatory T cells and to treat autoimmune diseases." (PMID 38461332, 2024). "Exploiting the suppressive capacities of Treg cells to enhance immune tolerance has been an emerging field to treat autoimmune diseases such as the application of low-dose interleukin-2 (IL-2) in RA." (PMID 38218985, 2024). "One SNP, i.e., rs6822844, is an intronic variant in the KIAA1109/Tenr/IL2/IL21 block and has been identified as a risk factor in several autoimmune diseases, including celiac disease, rheumatoid arthritis and type 1 diabetes." (PMID 38232165, 2024). "Dysregulated IL-2 function can lead to various immunological disorders, such as immunodeficiency, autoimmune diseases, or chronic inflammation." (PMID 38397895, 2024). "Micelacking components of the IL-2/IL-2R pathway exhibit a spontaneous development ofsevere autoimmune disease." (PMID 39076468, 2024). "Collectively, IL-2/SD-01 suppresses the immunity and demonstrates great therapeutic potential in a broad spectrum of autoimmune diseases." (PMID 38461332, 2024). "Multiple approaches have been pursued to overcome the therapeutic limitation of IL-2 in treating autoimmune diseases." (PMID 38461332, 2024). "In contrast to cancer treatment, where immunostimulatory effects are desirable, the treatment of autoimmune diseases with IL-2 should be focused on enhancing its immunosuppressive effects, while minimizing its immunostimulatory effects." (PMID 39169031, 2024).
autoimmune disease (continued). "The dysregulation of IL-2–mediated pathways has been identified as a key feature in the pathogenesis of several autoimmune disorders, resulting in a reduced number and altered function of Treg cells." (PMID 38432631, 2024). "Previous studies have suggested low-dose IL-2 as an effective treatment for several autoimmune diseases." (PMID 39720733, 2024). "Based on the safety of low-dose IL-2 in autoimmune diseases and its regulatory effects on T cells, we applied it over-the-counter to PD-1/PD-L1 inhibitor for treating BP and achieved good efficacy." (PMID 39720733, 2024). "IL-2 deficiency has been observed in various autoimmune diseases, including type 1 diabetes, RA, and SLE; however, the mechanism explaining these reduced IL-2 levels is not fully understood." (PMID 39124628, 2024). "The aim of this study was to compare levels of IL-2 in healthy NSDTRs to those with cancer or autoimmune disease and to compare levels of IL-12/IL-23p40 in healthy NSDTRs and beagles versus NSDTRs with cancer or autoimmune disease." (PMID 38773194, 2024). "Low-dose interleukin 2 (Ld-IL2) is increasingly being explored as an immune-modulating treatment for autoimmune diseases which mainly affect T cell subsets." (PMID 39482484, 2024). "IL-2 is vital for the survival and stability of Tregs, and low-dose IL-2 has shown promising outcomes in different autoimmune disease models." (PMID 38455364, 2024). "In general, levels of IL-4, IL-5, and IL-13 increased in allergic diseases; levels of IL-17 and IL-23 increased in autoimmune diseases; and levels of IL2 and IFN-ɣ increased in sarcoidosis and granulomatous diseases." (PMID 38529282, 2024). "IL-2 and IL-2/anti–IL-2 mAb immunocomplexes have been shown to have therapeutic efficacy against autoimmune diseases in preclinical studies via Treg promotions." (PMID 38807592, 2024). "As IL-2 plays an important role in negative selection in the thymus during T cell maturation and maintaining the proper function of Treg in peripheral, dysregulation of IL-2 can be found in several autoimmune diseases such as SLE, RA, and of course, MG." (PMID 39318549, 2024). "This study focuses on the application of novel low-dose IL2 therapy in these two autoimmune diseases i.e. SLE and RA, as well as the comparability of these new interventions’ efficacy and safety among patients of SLE and RA." (PMID 38646383, 2024). "In fact, in consistent with the findings in murine primary CD4+ T cells, TRAIL profoundly suppressed T cell proliferation and interleukin-2 (IL-2) production in human CD4+ T cells from patient with autoimmune diseases." (PMID 38532423, 2024). "The proof-of-concept Treg-biasing antibody against mouse IL-2 has triggered a campaign of discovering its counterparts against human IL-2 with potential clinical application in human autoimmune diseases." (PMID 38461332, 2024). "Currently, low-dose IL-2 therapy tried to treat various autoimmune diseases including RA, primary Sjögren's syndrome and SLE, has been shown to increase the number of CD4+CD25+FOXP3+Treg cells and achieved therapeutic results." (PMID 38240927, 2024). "Low-dose IL-2 can alleviate disease severity through modulating CD4 + T cell subsets in patients with autoimmune diseases." (PMID 38408917, 2024). "In recent years, Low-dose interleukin 2 (Ld-IL2) therapy has emerged as a promising treatment for a range of autoimmune diseases, including systemic lupus erythematosus (SLE), rheumatoid arthritis (RA), and dermatomyositis (DM)." (PMID 39482484, 2024). "This systematic review aims to compare the efficacy and safety of a novel immunotherapy with low-dose interleukin 2 (IL2) across two of the most prevalent autoimmune diseases i.e. systemic lupus erythematosus (SLE) and rheumatoid arthritis (RA)." (PMID 38646383, 2024).
autoimmune disease (continued). "By developing murine and human IL-2 orthogonal systems, they demonstrated a controlled activation of IL-2-dependent signaling pathways, providing insights into potential therapeutic strategies for both autoimmune diseases and cancer." (PMID 37516849, 2023). "Although the role of low-dose IL-2 in the treatment of autoimmune diseases has also attracted more attention, there are rare direct studies on the efficacy of low-dose IL-2 in psoriasis." (PMID 37596509, 2023). "Currently, low-dose IL-2 is being tested in clinical trials as a therapy for several autoimmune diseases; however, it remains a challenge to find the optimal effective IL-2 dosage for each individual." (PMID 37240014, 2023). "IL-15 trans-presentation can be blocked by targeting the cytokine receptor subunit IL-2/IL-15Rβ, and this is achieved through the use of Hu-Mik-β1 monoclonal antibody which is used now in clinical trials for treating those with autoimmune diseases." (PMID 37206670, 2023). "To conclude, there is a strong rationale for targeting Tregs using low doses of IL-2 to treat autoimmune diseases given the evidence from GWAS studies, mechanistic in vitro Treg studies, and experiments in animal models." (PMID 36399073, 2023). "This review will revisit the rationale behind using low-dose IL-2 as a therapy to treat autoimmune diseases and evaluate the outcomes of trials to date." (PMID 36399073, 2023). "Several clinical trials have evaluated the safety and efficacy of these engineered IL-2 molecules for cancer and autoimmune disorders." (PMID 37516849, 2023). "Due to the unique biological properties of IL-2, various IL-2-based immunotherapies have been considered for treating cancer and autoimmune diseases." (PMID 37827864, 2023). "Low‐dose IL‐2 therapy primarily promotes Treg cell expansion, which has been used to treat individuals with autoimmune diseases, whereas high‐dose IL‐2 administration induces both Treg and CD8+T cell expansions." (PMID 36684086, 2023). "In contrast, we have demonstrated before that a time-restricted increase in IL-2 during the onset of an autoimmune disease or alloreactive response is beneficial for the overall outcome of such diseases." (PMID 37275854, 2023). "Recognizing the therapeutic potential of IL-2, researchers are focused on engineering IL-2 for improved efficacy and safety in treating cancer and autoimmune diseases." (PMID 37516849, 2023). "Recently, low-dose IL-2 therapy has been expected to be effective against autoimmune diseases such as SLE because it can expand CD4+ Tregs." (PMID 36983342, 2023). "IL‐10 is a wide spectrum of anti‐inflammatory activity, and IL‐2 performs therapeutic ability in treating autoimmune diseases." (PMID 37506142, 2023). "Low-dose IL2-based therapies for autoimmune diseases have been shown to up-regulate Tregs, and complexing IL2 with anti-IL2 antibodies can prolong the half-life of IL2." (PMID 37147383, 2023). "Dysregulation can lead to autoimmune disorders and cancer, emphasizing the importance of understanding the biology, signaling pathways, transcription factors, and regulators of IL-2 and IL-2R." (PMID 37516849, 2023). "Interleukin-2 (IL-2), as a promising therapeutic agent for autoimmune diseases, is a cytokine that can selectively bind to the trimer IL-2 receptor (IL-2R) on regulatory T (Treg) cells and preferentially activate Treg cells." (PMID 37764520, 2023). "Consequences of defective IL-2 signalling are insufficient numbers or dysfunction of Treg and hence autoimmune disorders in human and mouse." (PMID 37741949, 2023). "Clinical trials to date have proven that low doses of IL-2 are safe and universally expand Tregs across a range of autoimmune diseases." (PMID 36399073, 2023). "Promising results have been obtained in human Treg adoptive transfer therapy and in animal models of autoimmune diseases using biologicals that increase Treg numbers in vitro, including IL-2/anti-IL-2 complexes and rapamycin." (PMID 37901208, 2023).